LINC00226 (long independently transcribed non-coding RNA 226)
Synonyms: formerly C14orf97; NCRNA00226
Gene: Long non-coding RNA gene on chromosome 14 (106,287,674 to 106,288,828, forward strand). Ensembl gene ENSG00000276210.
Diseases named in the same sentence as LINC00226 in open-access papers:
LINC00226 is named in the same sentence as 3 diseases in open-access papers, as found by Europe PMC text mining. Sharing a sentence is not in itself a finding about the gene and the disease. The quoted sentences say what the papers report.
glioma (1 paper, 2021). A benign or malignant brain and spinal cord tumor that arises from glial cells (astrocytes, oligodendrocytes, ependymal cells). "The CNA gains of LINC00226 and ADAM6 and the chromosome 16p11 loss were reconstituted in primary cells from both grade II/III gliomas and GBMs." (PMID 33981597, 2021).
cancer (1 paper, 2021). A tumor composed of atypical neoplastic, often pleomorphic cells that invade other tissues. "The expression of LINC0026 was also correlated to patient survival, and up-regulation of LINC00226 predicted poor prognosis and enhanced cell invasion, stemness, and proliferation in cancers." (PMID 33981597, 2021).
LINC00226 also shares sentences with these, for which no sentence is quoted: Mendelian diseases (1 paper).